SOD1 (superoxide dismutase 1)
Diseases named in the same sentence as SOD1 in open-access papers (continued):
Sharing a sentence is not in itself a finding about the gene and the disease.
prostate adenocarcinoma (2 papers, 2020 to 2023). "The GEPIA platform was used to measure the correlation between the antioxidant protein expression: Superoxide Dismutase 1 and 2 (SOD1 and SOD2) and peroxiredoxin 3 (PRDX3) with the NEK6 gene expression in prostate adenocarcinoma samples." (PMID 36672191, 2023).
Shock (2 papers, 2015 to 2016). The state in which profound and widespread reduction of effective tissue perfusion leads first to reversible, and then if prolonged, to irreversible cellular injury. "Thus, our results suggest that patients with septic shock had an impaired SOD1 response and increased oxidative stress, and this behavior was more pronounced in patients who developed AKI." (PMID 27709557, 2016).
Splenomegaly (2 papers, 2010 to 2021). Abnormal increased size of the spleen. "Unexpectedly, XDH-stable type did not improve the hemolytic anemia associated with the splenomegaly induced by SOD1 deficiency." (PMID 33805516, 2021). "In addition, splenomegaly and hypotension were more prevalent in patients with high SOD-1 and TNF-alpha levels compared to those with low levels of both factors (43.2% vs. 5.1% respectively; Fisher's test p = 0.02)." (PMID 20386593, 2010).
thalassemia (2 papers, 2020 to 2022). An inherited blood disorder characterized by a decreased synthesis of one of the polypeptide chains that form hemoglobin. "Therefore, the present study aimed to find out the status of 50-bp Insertion/deletion polymorphism of SOD1 gene promoter in thalassemia major cases and normal healthy individuals." (PMID 32461794, 2020). "While, calculating the allelic distribution Del allele ( SOD1 50bp Ins/ Del) was found to be more prevalent in the thalassemia patients with the frequency of 11.7% and 4% in cases and controls, respectively, and also statistically significant (OR=3.1955, 95% CI: 1.779-5.738, P= 0.0001)." (PMID 32461794, 2020). "In the present study, we investigated whether genetic polymorphisms in SOD1 contribute to the risk of developing oxidative stress in thalassemia patients in hospital based case–control study." (PMID 32461794, 2020). "Since in this study only a fraction of thalassemia patients took SOD1 enzyme activity, when compared with in genotype, their serum SOD activity was not statistically significantly vary between different genotypes in patients (P>0.0001)." (PMID 32461794, 2020).
thyroid tumor (2 papers, 2017 to 2019). A benign or malignant neoplasm affecting the thyroid gland. "The average expression for SOD1 shown as Log2 median-centered intensity in the normal thyroid is 1.46 and remains at the same level in thyroid tumors." (PMID 29478325, 2019). "Interestingly, the database has suggested relatively high SOD1 and SOD3 gene expression in general in normal thyroid tissue and thyroid tumors." (PMID 29478325, 2019).
trisomy 21 (2 papers, 2018 to 2024). A chromosomal disorder consisting of the presence of an extra chromosome 21. "For example, superoxide dismutase 1 (SOD1) activity, which is increased by 1.5 times in trisomy 21 children, belongs to the first group, while glutathione peroxidase (GPX1), which is also increased, belongs to the second one15." (PMID 29445163, 2018).
Ureteral obstruction (2 papers, 2021 to 2024). Obstruction of the flow of urine through the ureter. "SOD1 deficiency augmented salt sensitive–hypertension and tubulointerstitial fibrosis in unilateral ureteral obstruction (UUO) mice, whereas SOD1 overexpression using transgenic mice or chronic tempol treatment abolished those findings in UUO mice." (PMID 33477607, 2021).
ZIKV infection (2 papers, 2025). "Our results showed that ALIX, CD9 (exosomal biogenesis), SOD-1, and CAT (regulation of oxidative stress) had decreased protein expression levels during ZIKV infection, in contrast to the mock-infected cells." (PMID 40572291, 2025).
adenoma (1 paper, 2019). A neoplasm arising from the epithelium. "Similarly, in adenoma development-related NOX1–5 and SOD1–3 gene expression, the progression of primary colon adenocarcinoma to metastatic cancer shows large variation in redox gene expression in individual patients compared to the normal colon tissue values." (PMID 29478325, 2019).
age-related hearing loss (1 paper, 2020). "For instance, several antioxidant genes, including SOD2, GST or UCP, have been associated to age-related hearing loss and genetic mouse models deficient for antioxidant genes, including Nrf2, Sod1 or genes regulating the mTOR pathway, show accelerated age-related hearing loss." (PMID 32000019, 2020).
asphyxia (1 paper, 2020). A state of general hypoxia and hypercapnia (abnormally elevated carbon dioxide (CO2) levels in the blood), resulting in acidosis, which affects all tissues in the body. "Similarly, in our study, the rats subjected to perinatal asphyxia expressed higher levels of GPx3 and SOD-1 in the brain." (PMID 32816128, 2020).
B cell lymphomas (1 paper, 2015). "Along similar lines, we recently reported that a higher ratio of Bcl-2pSer70 to superoxide dismutase 1 (SOD1) was associated with disease severity or poor outcome in human B cell lymphomas; SOD1 is involved in the regulation of intracellular O2•−." (PMID 26430964, 2015).
Batten disease (1 paper, 2025). "Tofersen (Qalsody), an ASO, targets mutant SOD1 mRNA in ALS, and Milasen, a compassionate-use ASO, was developed for Batten disease (CLN7 variant)." (PMID 40533746, 2025).
Brain atrophy (1 paper, 2021). Partial or complete wasting (loss) of brain tissue that was once present. "Our results show that only male SOD1-G93A/low mice present minor brain atrophy in the cervical ventral horn, while female animals and other ventral horn regions seem not to be affected." (PMID 34248499, 2021). "As we observed here a median survival rate of 33.6 weeks in male and 36.9 weeks in female SOD1-G93A/low mice, it can be assumed that changes in brain atrophy were not yet measurable by a reduced region size at the time of evaluation." (PMID 34248499, 2021).
brain hemorrhage (1 paper, 2025). "Functionally, SOD1 deletion was associated with enhanced incidence, number and size of brain hemorrhage in a mouse model of spontaneous ICH, implicating a key role of SOD1 in the pathophysiology of ICH." (PMID 40320180, 2025).
Cerebellar hypoplasia (1 paper, 2023). Cerebellar hypoplasia is a descriptive term implying a cerebellum with a reduced volume, but a normal shape and is stable over time. "Comparing these four models suggests that at least one gene in the region that is trisomic in both Ts1Cje and Ts65Dn mice but is not trisomic in Ts1Rhr mice (Sod1 to Setd4 and Ripk4 to Zbtb21) contributes to cerebellar hypoplasia." (PMID 36995257, 2023).
colon adenoma (1 paper, 2019). An adenoma that arises from the colon. "SOD1 mRNA expression in colon adenoma is increased by 6.2% (SD 5.2), indicating relatively stable SOD1 expression in the early phase of tumorigenesis." (PMID 29478325, 2019).
erysipelas (1 paper, 2017). An infection of the upper layers of the skin caused by species of streptococcus. "Our data corroborates this observation, as a significant association was demonstrated between G allele of SOD1 G7958A and predisposition to erysipelas." (PMID 28512644, 2017). "We observed an association between SOD1 (G7958A) and localization of infection, where higher proportion of G/A and A/A genotypes were found in patients who had erysipelas on the upper limb." (PMID 28512644, 2017). "We observed an association between SOD1 (G7958A) and localization of infection, where higher proportion of G/A and A/A genotypes was found in patients who had erysipelas on the upper limb, (p = 0.041)." (PMID 28512644, 2017). "The presence of SOD1 G7958, SOD2 T2734, and CAT C262 alleles was linked to erysipelas' predisposition." (PMID 28512644, 2017). "Currently, our knowledge on the association between SOD1, SOD2, and CAT gene expression and severity of erysipelas is limited." (PMID 28512644, 2017). "Comparing 71 erysipelas patients to 55 age-matched healthy individuals, we sought for CAT, SOD1, and SOD2 single polymorphism mutation (SNPs) interactions with erysipelas' predisposition and serum cytokine levels in the acute and recovery phases of erysipelas infection." (PMID 28512644, 2017). "Therefore, we sought to determine whether single-nucleotide polymorphisms (SNPs) in the genes encoding SOD1, SOD2, CAT, and cytokine levels and their interaction can serve as susceptibility markers for erysipelas." (PMID 28512644, 2017). "Also, correlation between expression of SOD1, SOD2, and catalase genes and activation of inflammatory cytokine in erysipelas still remain unknown." (PMID 28512644, 2017). "There were lack of differences in the distribution of SOD1 (G7958A), SOD2 (T2734C), SOD2 (C60T), and CAT (C262T) SNPs in subjects with erysipelas based on gender, multiplicity, and severity of the disease (p > 0.05)." (PMID 28512644, 2017).
eyelid inflammation (1 paper, 2022). "Since SOD1 attenuates ocular inflammation by scavenging ROS, a lower level of SOD1 in Fut1 KO mice might lead to eyelid inflammation and MGD." (PMID 36012728, 2022).
Fanconi Anaemia (1 paper, 2022). "Moreover, mice lacking the cytosolic Cu/Zn superoxide dismutase 1 (Sod1) and the Fanconi Anaemia DNA repair pathway gene FancC develop hematopoietic failure and liver steatosis." (PMID 35136057, 2022).
gastric tumour (1 paper, 2019). "Moreover, JS‐K administration also significantly suppressed the expression of SOD1 and catalase in gastric tumour tissues, indicating that JS‐K down‐regulates SOD1 and catalase in vivo." (PMID 30672108, 2019). "Moreover, JS‐K administration (1.5 and 3 mg/kg) significantly decreased SOD1 and catalase activity in gastric tumour tissues; therefore, JS‐K could decrease SOD1 and catalase activity in vivo and in vitro, which would also contribute to JS‐K‐induced ROS accumulation." (PMID 30672108, 2019).
heroin dependence (1 paper, 2017). Physical and psychological dependence on the drug heroin. "The aims of the present study are to evaluate the influence of the Ins/Del polymorphism on the SOD1 mRNA levels in human normal peripheral blood cells and investigating the association between this genetic polymorphism and risk of heroin dependence." (PMID 29165112, 2017). "Although the association between GSTs polymorphisms and susceptibility to drug dependency has been reported, there are no study investigating the association between the Ins/Del polymorphism of the SOD1 and risk of heroin dependence." (PMID 29165112, 2017).
Hodgkin’s disease (1 paper, 2020). "In the case of Hodgkin’s disease and testicular cancer, SOD1 expression was comparable with fertile men." (PMID 32942548, 2020).
Hyperkalemia (1 paper, 2024). An abnormally increased potassium concentration in the blood. "The activated morphology of SOD1 spinal astrocytes was associated with the results from volume measurements, which showed decreased swelling of these cells during hyperkalemia." (PMID 39449756, 2024).
hypertensive heart disease (1 paper, 2021). Abnormal enlargement of the heart resulting from long-standing hypertension. "Our findings indicated that the targeted genes of AS-IV against hypertensive heart disease are involved in oxidative stress and inflammation, including SOD2, SOD1, IL-6, TNF, and IL-1β." (PMID 34803698, 2021). "The findings of the PPI network indicated that SOD1 and SOD2 were predicted as the potential genes of AS-IV in the treatment of hypertensive heart disease." (PMID 34803698, 2021). "In the present study, we found that AS-IV up-regulated the expression of SOD1 and SOD2, improved the activities of SOD and GSH, and decreased the MDA level, indicating that AS-IV inhibited the progression of hypertensive heart disease via inhibition of oxidative stress." (PMID 34803698, 2021).
intestinal tumor (1 paper, 2022). "Thus, our finding that SOD1 suppresses ectopic Paneth cell differentiation could suggest a self-sustaining mechanism that prevents intestinal tumor formation." (PMID 36266264, 2022).
Miscarriage (1 paper, 2021). A pregnancy that ends at a stage in which the fetus is incapable of surviving on its own, defined as the spontaneous loss of a fetus before the 22th week of pregnancy. "SOD1 plasma activity was 5.43 ± 0.69 nmol/min/ml in recurrent miscarriage group and 6.11 ± 0.73 nmol/min/ml in healthy controls." (PMID 34656123, 2021).
Mitochondrial myopathy (1 paper, 2015). "Mitochondrial myopathy is reported in cases with CHCHD10 and SOD1 mutations." (PMID 26213621, 2015).
monocytopenia (1 paper, 2016). "CSF1R has a key role in triggering hematopoietic stem cells to differentiate into monocytes, we thus assessed whether the reduced infiltration of macrophages into the nerve induced by GW2580 treatment of SOD1 mice was due to monocytopenia." (PMID 27174644, 2016).
Mydriasis (1 paper, 2014). Abnormal dilatation of the iris. "Animal studies using the ALS-mouse model (the superoxide dismutase 1, SOD1, knockout mouse) have demonstrated persistent mydriasis with infusion of morphine compared to wild type." (PMID 24961916, 2014).
myelomeningocele (1 paper, 2025). Myelomeningocele is the most severe form of spina bifida. "Along these lines, investigation of SNPs within the SOD1 and SOD2 genes, yielded four SNPs in SOD1 (rs202446, rs202447, rs4816405, and rs2070424) and one SNP in SOD2 (rs5746105) that were significantly associated with myelomeningocele risk." (PMID 40666233, 2025).
Neurofibrillary tangles (1 paper, 2020). Pathological protein aggregates formed by hyperphosphorylation of a microtubule-associated protein known as tau, causing it to aggregate in an insoluble form. "A subset of the proteins identified in the APPswe/PS1dE9 model were also identified as losing solubility in mice that model neurofibrillary tangle (NFT) pathology, superoxide dismutase 1 (SOD1) pathology, and α-synuclein pathology." (PMID 32252825, 2020).
normal tension glaucoma (1 paper, 2019). "Most known mouse models of normal tension glaucoma, like excitatory amino-acid carrier 1 (EAAC1), glutamate/aspartate transporter (GLAST) and superoxide dismutase 1 (SOD1) knockout mice are actually models of increased oxidative stress." (PMID 30914695, 2019).
optic atrophy (1 paper, 2009). A disorder characterized by loss of optic nerve fibers. "Treatment with antioxidants or superoxide dismutase (SOD1), as well as over-expression of human SOD1 did reverse the glossy phenotype, further indicating the important role of ROS in etiology of optic atrophy." (PMID 19221591, 2009).
orchitis (1 paper, 2021). Inflammation of one or both testes due to viral or bacterial infections. "The level of key enzymes Ivd, Uqcrb, Sod1, Akr1a1, and Cat, which were members of the gene set Hallmark reactive oxygen species, were decreased during orchitis." (PMID 35111154, 2021). "Uqcrb, Sod1, Zfp30, and Zzz3 negatively regulated collagen expression during orchitis." (PMID 35111154, 2021).
ovarian adenocarcinoma (1 paper, 2025). An adenocarcinoma that arises from the ovary. "Treatment with CUR alone significantly inhibited the growth of human ovarian adenocarcinoma SKOV-3/CDDP CDDP-resistant subline cells by inhibition the gene expression of the antioxidant enzymes (SOD1, SOD2, GPX1, CAT, and HO1), transcription factor NFE2L2 and signaling pathway (PIK3CA/AKT1/MTOR)." (PMID 39859517, 2025).
ovarian tumor (1 paper, 2024). "Additionally, the expression levels of HSPA8 and SOD1 were higher in high-grade serous ovarian cancer samples compared to non-malignant ovarian tumor tissues, while RPL13A, PSMA5, and RPSA showed the opposite trend." (PMID 38166541, 2024). "Furthermore, immunohistochemistry staining (IHC) and real-time quantitative PCR (RT-qPCR) were employed for the validation of the expression and biological functions of core proteins, including HSPAA1, HSPA8, SOD1, and transcription factors SREBF2 and GTAT2, in ovarian tumors." (PMID 38166541, 2024). "RT-qPCR results showed that SOD1 exhibited consistent expression with HSP90AA1 and HSPA8, while SREBF2 and GTAT2 were highly expressed in non-malignant ovarian tumor tissues and significantly decreased in high-grade serous ovarian cancer samples." (PMID 38166541, 2024).
paroxysmal dyskinesia (1 paper, 2023). Paroxysmal dyskinesia (PD) is a rare heterogenous group of movement disorders manifesting as abnormal involuntary movements that recur episodically and last only a brief time. "A variant within the same SOD1 gene is also responsible for paroxysmal dyskinesia in the Markiesje dog breed." (PMID 38003185, 2023).
peripheral motor neuropathy (1 paper, 2015). "Sod1−/− mice develop a progressive peripheral motor neuropathy, in which motor axons retract from neuromuscular junctions resulting in muscle denervation." (PMID 25468678, 2015).
peripheral nerve injury (1 paper, 2010). Injury to a peripheral nerve. "The neuroprotective effects of MT3, which are presumably due to its metal-chelating and antioxidative effects, are evident in epileptic brain injury, cortical cryolesions, a mutant superoxide dismutase 1 (SOD1[G93A]) mouse model of ALS, and peripheral nerve injury." (PMID 20974010, 2010).
pharyngitis (1 paper, 2026). Inflammation of the throat most often caused by viral and bacterial infections. "High DS superoxide dismutase 1 (SOD1) mRNA expression was consistently found and was strongly associated with an increased odds of inflammatory co-occurring conditions such as pharyngitis." (PMID 41646381, 2026).
Pneumocystis pneumonia (1 paper, 2019). "Genotype SOD2 was observed only in Pneumocystis pneumonia patients while the genotype SOD1 was observed in both colonized and Pneumocystis pneumonia patients." (PMID 31681723, 2019).
polycythemia (1 paper, 2017). Abnormally high mass or concentration of red blood cells in the blood, either due to an increase in erythropoiesis or a decrease in plasma volume. "It seems that in contrast to mice with genetic IRP1 ablation, in Sod1-/- mice showing only partial decline in renal IRP1, regulatory axis IRP1-HIF2α and its impact on erythropoiesis and the occurrence of polycythemia are not altered as attested by normal peripheral erythrocyte count." (PMID 28542246, 2017).
Progressive Spastic Tetraplegia and Axial Hypotonia (1 paper, 2024). "Furthermore, homozygous pathogenic variants in SOD1 have recently been associated with SOD1 deficiency and a very early-onset upper motor neuron-dominant phenotype, called Progressive Spastic Tetraplegia and Axial Hypotonia (STAHP)." (PMID 38540369, 2024).
respiratory paralysis (1 paper, 2018). Complete or severe weakness of the muscles of respiration. "Denervation of the diaphragm muscle is responsible for lethal respiratory paralysis in SOD1-G93A mice and ALS." (PMID 29460776, 2018).
somatotropinoma (1 paper, 2018). "Rat somatotropinoma-derived GH3 cells secrete SOD1, which, via activation of a muscarinic M1 receptor, reduces the activity of the MAPK1 signaling pathway, by inhibiting MAPK3 phosphorylation, reducing cell proliferation." (PMID 29507682, 2018).
thromboembolic disease (1 paper, 2023). "Genes such as superoxide dismutase 1 (SOD1, one of the three human superoxide dismutases) and factor V Leiden (linked to a hypercoagulable condition and thromboembolic disease) were evaluated as potential factors implicated in the pathogenesis of SSNHL." (PMID 37893435, 2023).
transport (1 paper, 2023). "Sirt3 can restore neuronal mitochondrial fragmentation and transport disorders caused by SOD1 mutations to a certain extent, reducing neuronal death and protecting against mitochondrial alterations in the SOD1-mutant neurons." (PMID 37238605, 2023).